INS (insulin)
Diseases named in the same sentence as INS in open-access papers (continued):
Sharing a sentence is not in itself a finding about the gene and the disease.
type 2 diabetes (continued). "The enzyme 11β-hydroxysteroid dehydrogenase type 1 (11β-HSD1) is a target for novel type 2 diabetes and obesity therapies based on the premise that lowering of tissue glucocorticoids will have positive effects on body weight, glycemic control, and insulin sensitivity." (PMID 24169553, 2013). "This study has shown that hypoglycaemia is also associated with increased accident risks in people with type 2 diabetes receiving antidiabetes drugs without insulin." (PMID 23121373, 2013). "In Zucker diabetic fatty rats representing a type 2 diabetes model and in a type 1 diabetes animal model with streptozotocin an impaired insulin secretion and signaling and an increased hepatic gene expression of CBS and BHMT representing the branch-point enzymes of C1-metabolism have been reported." (PMID 23472083, 2013). "Nevertheless, this parameter not only exhibited a close correlation with the glucose clamp-derived insulin sensitivity index, but it also was one of the best predictors of incident type 2 diabetes among surrogate estimates of IR based on assays of fasting insulin and glucose." (PMID 23578341, 2013). "An increased risk of fall-related fractures has been associated with hypoglycaemia in people with type 2 diabetes receiving oral antidiabetes drugs in Medicare, although not excluding use of insulin." (PMID 23121373, 2013). "According to Boden & Shulman, the responsiveness of peripheral tissues to insulin may be damaged due to an increase in the concentration of FFA, affecting the insulin signaling pathway and thus leading to type 2 diabetes." (PMID 23496920, 2013). "Subjects of South Asian ethnicity with type 2 diabetes, despite being younger and leaner, had higher basal endogenous glucose production, indicating higher hepatic insulin resistance, and a trend towards higher use of carbohydrates as fasting energy substrate compared to Nordic subjects." (PMID 24391858, 2013). "When men with type 2 diabetes were further classified by treatment status, use of oral antihyperglycemia agents or insulin was associated with an increased odds of LUTS than men without type 2 diabetes." (PMID 23421436, 2013). "In recent human studies, almond consumption was shown to have beneficial effects on blood glucose levels in individuals with type-2 diabetes and prediabetes, with statistically-significant improvements in fasting levels of glucose, insulin, insulin sensitivity and LDL-cholesterol." (PMID 24113641, 2013). "In order to improve patient outcomes, it is essential to understand the medication use behavior of comparatively newer therapies such as exenatide BID (exenatide), a glucagon like peptide 1 (GLP-1) receptor agonist and insulin glargine (glargine) for the treatment of type 2 diabetes." (PMID 23799930, 2013). "Of those with type 2 diabetes, only 17.8% (n = 179) were using insulin." (PMID 24349036, 2013). "In addition, people with Type 2 diabetes have impaired insulin secretion and GLP-1 production postprandially." (PMID 23776669, 2013). "Apoptosis is thought to be one of the major factors in decline of beta cell mass in both type 1 and type 2 diabetes and the failure of beta cell mass to expand in order to compensate for increasing insulin resistance is another key factor in the development of type 2 diabetes." (PMID 23840838, 2013). "Impaired insulin-stimulated glucose transport by glucose transporter 4 (GLUT4) is a well-documented contributor to the reduced glucose clearance found in subjects with type 2 diabetes mellitus (T2DM)." (PMID 23776597, 2013). "Among Type 2 diabetics, NSNHEs are not limited to those who are insulin-dependent." (PMID 22825805, 2013). "Type 2 diabetes results in part from diminished insulin action in peripheral tissues such as skeletal muscle and liver, and in part from a failure of the pancreatic β-cells to compensate by increasing insulin secretion in response to elevated blood glucose levels." (PMID 23469261, 2013).
type 2 diabetes (continued). "Therefore, female patients with type 2 diabetes are more likely to develop subjective sleep disorders during insulin therapy than males." (PMID 23383010, 2013). "Basal insulin provides an effective method for initiating insulin therapy in people with Type 2 diabetes, resulting in significant improvements in glycaemic control, lower rates of hypoglycaemia and less weight gain than either prandial or premixed insulin regimens." (PMID 22998363, 2013). "A cholesterol synthesis marker desmosterol significantly predicted an increase, and two absorption markers (campesterol and avenasterol) a decrease in the risk of hyperglycemia and incident type 2 diabetes in a 5-year follow-up of the METSIM cohort, mainly attributable to insulin sensitivity." (PMID 23840693, 2013). "Altered insulin secretion contributes to the pathogenesis of type 2 diabetes." (PMID 23516528, 2013). "Few of our older patients with type 2 diabetes were using insulin." (PMID 24349036, 2013). "Clinical characteristics of 140 patients with type 2 diabetes on insulin therapy." (PMID 23383010, 2013). "However, in patients with long-standing type 2 diabetes, use of a prandial insulin is often required to maintain glycaemic control 2,8." (PMID 23061470, 2013). "This strategy might prove valuable in regulating insulin secretion and hence, slowing development of type 2 diabetes by itself and/or in combination with existing therapies." (PMID 23516528, 2013). "The results suggest that insulin therapy decreases PEDF in the blood of type 2 diabetes patients." (PMID 24367624, 2013). "Adipose tissue secretes a number of bioactive molecules, such as resistin, TNF-α, and IL-6 collectively called adipokines, which affect peripheral insulin sensitivity and may be important players in the development of type 2 diabetes and atherosclerosis." (PMID 23484124, 2013). "In type 2 diabetes, hyperglycemia caused due to impairment in insulin secretion combined with or without impairment of insulin action." (PMID 23936668, 2013). "Notably, NGT 1 h-high exhibit a reduction in insulin clearance similar to the one observed in IGT individuals, who are considered at high risk for type 2 diabetes." (PMID 24194886, 2013). "In type I diabetes, autoimmune reaction to β cells leads to destruction of insulin-producing cells, and in type II diabetes, cumulative cell damage evoked by various stresses induces β-cell dysfunction, eventually resulting in insufficient insulin supply and a reduction in β-cell mass." (PMID 23593212, 2013). "We show in one region that HHEX may contribute to type 2 diabetes phenotypes including hyperglycemia and insulin insensitivity; in addition, our data suggests two neighboring genes may also contribute to the risk identified by GWAS." (PMID 23445342, 2013). "Moreover, the severity of the insulin-resistant state characteristic of type 2 diabetes has been shown to preclude the expected exercise increase in glucose uptake by muscle cells." (PMID 23536769, 2013). "PCOS and type-2 diabetes share common insulin signaling defects in muscle and fat." (PMID 23690868, 2013). "The hypothesis was initially based on observations in monogenic diabetes, but subsequent evidence has supported the foetal insulin hypothesis in type 2 diabetes." (PMID 24336895, 2013). "Interestingly, total daily insulin need was higher both in type 2 diabetes and GDM treated with NPH while a higher need for short-acting analogue was found in type 2 diabetic women only." (PMID 23840206, 2013). "It is generally classified as type I diabetes, in which there is absolute lack of insulin caused by pancreatic beta cell destruction and type II diabetes, in which there is insufficient insulin secretion or insulin resistance in peripheral tissues." (PMID 23476801, 2013).
type 2 diabetes (continued). "In people with type 2 diabetes receiving antidiabetes drugs without insulin, hypoglycaemia was associated with a significantly higher risk of accidents resulting in hospital visits, including accidents related to driving and falls." (PMID 23121373, 2013). "Reduced insulin clearance has been shown to predict the development of type 2 diabetes." (PMID 24194886, 2013). "Hence, to maintain normoglycemia, the most desirable treatment for type 2 diabetes should target improvement of beta-cell dysfunction and insulin resistance simultaneously." (PMID 24188631, 2013). "Most type II diabetics have elevated insulin and insulin-like growth factor (IGF)-1 levels at baseline, which are mitogenic to tumor cells via activation of downstream signaling cascades that mediate proliferation, migration/invasion, angiogenesis, and treatment resistance." (PMID 24133632, 2013). "Also, DPP-IV inhibition can preserve pancreatic β-cell mass and function by increasing the number of insulin positive β-cells in islets of mice with type 2 diabetes." (PMID 23382843, 2013). "Indeed, three members of this subnetwork (i.e. MAPK1, INSR, SOCS3) belong to the Type II diabetes mellitus pathway, which fall into the bigger insulin signaling pathway together with SHC1 and ELK1." (PMID 23885764, 2013). "Importantly, given the involvement of APP in insulin regulation and neurodegeneration, its upregulation in blood of Parkinson's disease and type 2 diabetes provides a novel link between both diseases." (PMID 24376773, 2013). "Our study showed that poorer sleep quality in patients with type 2 diabetes using insulin therapy." (PMID 23383010, 2013). "Current evidence suggests that ILPS may represent a valuable option in the management of diabetic patients, primarily those with type 2 diabetes, requiring insulin treatment regimens." (PMID 23840206, 2013). "Liraglutide combined with insulin may be the best treatment option for poorly controlled type 2 diabetes and abdominal obesity." (PMID 23153177, 2012). "The aim of the study was to test whether CACNA1E common variability affects beta cell function and/or insulin sensitivity in patients with newly diagnosed type 2 diabetes." (PMID 22427875, 2012). "Two hallmarks of type 2 diabetes are decreased insulin secretion and a reduced incretin effect." (PMID 23056280, 2012). "Although the metabolic disorders typically associated with Type 2 diabetes are usually not present in Type 1 diabetes, insulin alters the vascular function in Type 1 diabetes as well." (PMID 22262970, 2012). "It has been shown that the crosstalk between insulin signaling and the mitochondria may be involved in the etiology of type 2 diabetes." (PMID 23236286, 2012). "As a result, cells lacking Cx36 do not release insulin in a normal pulsatile fashion, show an increased basal release of the hormone, and a decreased insulin output in response to glucose, three alterations reminiscent of the defects observed in prediabetic states and type 2 diabetes." (PMID 22848521, 2012). "To investigate if OA improves insulin sensitivity through a similar mechanism, we measured the triglyceride levels in plasma and liver because a reduction in hepatic steatosis is able to normalize glycemia in type-2 diabetes." (PMID 22860063, 2012). "In addition, UCP-2-/- mice demonstrate enhanced insulin secretory capacity after a high-fat diet due to improved β-cell functions in a type 2 diabetes animal model." (PMID 22360800, 2012). "Type 2 diabetes patients, mostly over 50 years old (although more and more young people develop type 2 diabetes) with additional health problems (eg, cardiovascular disease), in the early stages are often characterized by high plasmatic insulin concentration." (PMID 23612026, 2012). "However, CLA has been shown to exhibit some adverse effects, including reduction in insulin sensitivity in subjects with type 2 diabetes and augmentation of the pre-existing insulin resistance." (PMID 23251142, 2012).
type 2 diabetes (continued). "An increased proinsulin/insulin ratio is a characteristic finding at the onset of type 2 diabetes." (PMID 23077502, 2012). "Unlike type 2 diabetes which is caused by the loss of insulin sensitivity, type 1 diabetes (T1D) is manifested by the absolute deficiency of insulin secretion due to the loss of β mass by autoimmune response against β-cell self-antigens." (PMID 22454627, 2012). "This 12-week double-blind, randomized, placebo (PL)-controlled proof-of-concept study was performed to determine if the MMP inhibitor (MMPI), doxycycline, decreased global markers of inflammation and enhanced muscle insulin sensitivity in obese people with type 2 diabetes (DM2)." (PMID 23025537, 2012). "However in Type 2 diabetes where endogenous insulin secretion is preserved, excellent glycaemic control can be achieved using basal (intermediate or long acting) insulin without rapid or short acting prandial insulin." (PMID 22681724, 2012). "Furthermore, 10 mg of mitiglinide once a day at lunchtime to twice daily injections of premixed insulin are effective for type 2 diabetes treatment." (PMID 22748110, 2012). "Various studies have shown that the increase in insulin levels may be a compensatory mechanism to the decreased peripheral insulin sensitivity in response to obesity, ultimately leading to islet failure and to type 2 diabetes." (PMID 22715406, 2012). "For example, some people with type 2 diabetes using insulin treatment may have self-identified as having type 1 diabetes, while for self-reported complications or co-morbidities, some people may not be aware of specific diagnoses." (PMID 23110382, 2012). "GBR's antihyperglycemic effects and lower insulin index suggest that the core problem in type 2 diabetes could be improved by GBR, thereby reducing the chances of other secondary perturbations and hyperglycemia-induced complications from arising." (PMID 23304216, 2012). "Our results further support the idea that dietary supplementation using n-3 LC-PUFA could improve the efficacy of TZDs, as well as other insulin-sensitizing and hypolipidemic pharmaceuticals used for the treatment of obese and type 2 diabetic patients." (PMID 22952760, 2012). "In Malaysia, studies have reported very low usage of insulin among patients with type 2 diabetes." (PMID 22545648, 2012). "Type II diabetes mellitus is a complex heterogeneous group of metabolic conditions characterized by an increased level of blood glucose, due to impairment in insulin action and/or insulin secretion." (PMID 23843827, 2012). "Insulin clearance rate is heritable and is reduced in obesity and Type-2 diabetes." (PMID 23308073, 2012). "Monogenic disorders include syndromes characterized in early studies that resemble type 2 diabetes caused by mutations in the insulin gene in non-neonatal patients." (PMID 22509386, 2012). "While insulin-stimulated glucose utilization is impaired in type 2 diabetes, physical exercise results in regular GLUT4 translocation and glucose uptake, mediated by the activation of 5′-AMP-activated kinase (AMPK), a cellular “fuel sensor” which detects ATP depletion induced by several conditions." (PMID 22778921, 2012). "A large proportion of patients with Type 2 diabetes will eventually require insulin." (PMID 22681724, 2012). "Therefore, extragenetic, outbred Sprague–Dawley rats are commonly fed a HFD in combination with low-dose streptozotocin (STZ) to establish type 2 diabetes, characterized by insulin resistance and β cell dysfunction." (PMID 23272147, 2012). "If hyperinsulinemia was to be implicated in laminin regulation in type 2 diabetes, the renal parenchyma would have to be responsive to insulin, unlike the liver which is insulin resistant." (PMID 22454628, 2012). "Low blood levels of magnesium (hypomagnesemia) are often seen in individuals with type 2 diabetes, and magnesium might improve insulin sensitivity in healthy individuals and in type 2 diabetics." (PMID 22415230, 2012).
type 2 diabetes (continued). "Moreover transgenic mice overexpressing PED/PEA-15 (TgPED) to levels comparable to those occurring in type 2 diabetic patients, display altered glucose tolerance and impaired insulin secretion." (PMID 21780113, 2012). "However, previous studies in adults with type 2 diabetes showed that food supplementation with psyllium led to improved glucose metabolism, as examined by post-prandial glucose and insulin excursion." (PMID 22848584, 2012). "Type 2 diabetes (formerly called non-insulin-dependent or adult-onset diabetes) is caused by the body’s ineffective use of insulin." (PMID 23181626, 2012). "A hypothesis further supported by increased adiponectin and peroxisome proliferator-activated receptor γ-2 (PPARγ-2) gene (two well-known insulin sensitizers) in centenarians and long-lived men, whose type 2 diabetes incidence was also dramatically decreased." (PMID 22500228, 2012). "Likewise, reduced p70S6K1 (T389) phosphorylation in response to insulin was previously reported as a characteristic feature of adipocytes obtained from patients with type 2 diabetes." (PMID 22969728, 2012). "Recent genome wide association studies have found the islet-restricted Zinc transporter ZnT8 (SLC30A8) as a potential controller of insulin secretion and hence may modulate the risks of developing type 2 diabetes." (PMID 22515411, 2012). "Respondents with type 2 diabetes were less focused on adjusting the insulin dose." (PMID 22397638, 2012). "Therefore, improvements of insulin action and β-cell function are important mechanisms for the pharmacological treatment of type-2 diabetes." (PMID 22860063, 2012). "However, the concentrations of insulin used in those experiments are often much higher than those reached in human plasma and tissues during insulin treatment for type 2 diabetes." (PMID 23209929, 2012). "Insulin has long been known to form amyloid fibrils and has been extensively studied because of problems in its production, delivery, and storage for use in treating type II diabetes and also as a model system." (PMID 22848214, 2012). "Domestic broiler chickens rapidly accumulate adipose tissue due to intensive genetic selection for rapid growth and are naturally hyperglycemic and insulin resistant, making them an attractive addition to the suite of rodent models used for studies of obesity and type 2 diabetes in humans." (PMID 22938590, 2012). "The inability of β cells to secrete enough insulin produces type 2 diabetes." (PMID 23316348, 2012). "The patient suffered from type II diabetes mellitus and had been on insulin therapy for 20 years." (PMID 22252286, 2012). "Furthermore, this points to the existence of a link between insulin, cognitive decline and dementia, and type 2 diabetes." (PMID 22500228, 2012). "In contrast, amelioration of insulin sensitivity by the PPARγ agonists, pioglitazone, and rosiglitazone, is accompanied by an increase in subcutaneous fat mass, but not in visceral fat weight in obese rats, and also in the patients with type 2 diabetes." (PMID 22253646, 2012). "In contrast, we and others have shown that adults who have parents or siblings with type 2 diabetes may have an impaired ability to improve insulin sensitivity following either short-term (3–9 days) or longer-term (26 weeks) aerobic exercise training." (PMID 22666560, 2012). "In addition, the development of resistance to the action of both leptin and insulin, which can occur with age, obesity and inflammation, appears to have a prime role in the pathogenesis of obesity, type 2 diabetes, and other metabolic disorders." (PMID 23115649, 2012). "Accordingly, we hypothesized that AT2 receptor stimulation by C21 might contribute to possible insulin-sensitizing/anti-diabetic effects in type 2 diabetes, with PPARγ activation." (PMID 23155382, 2012).